ALB (albumin)
Diseases named in the same sentence as ALB in open-access papers (continued):
Sharing a sentence is not in itself a finding about the gene and the disease.
infection (continued). "In the context of LS infection, expression of typical hepatocyte markers such as albumin, tryptophan 2,3-dioxygenase, and liver fatty acid binding protein (Lfabp) was not identified in MBA-differentiated JM8.N4 and E14 cells, confirming the lack of characteristic hepatocyte-like features." (PMID 32442532, 2020). "Infection with IBV in laying hens can negatively influence egg production, resulting in poor-quality eggs, such as misshapen, miscolored, thin, rough-shelled or shell-less eggs and eggs with watery albumin, meat or blood spots, which can peak at around two weeks post-infection." (PMID 32987684, 2020). "Albumin (half-life of 14–20 days) is widely used to assess the nutritional status of patients, but is also a negative acute-phase protein and thus decreases when a patient experiences physiological stress (e.g., infection, surgery or trauma)." (PMID 31936748, 2020). "In this regard, further studies are necessary to confirm whether interactions exist between serum calcium level and serum albumin level or age regarding infection-related death in hemodialysis patients." (PMID 32286455, 2020). "Whereas, the [3H]preS1 binding assays were performed in NTCP-HEK293 cells in pure DMEM, the infection experiments needed to be performed with NTCP-HepG2 cells in HGM containing significant amounts of bovine serum albumin (BSA) as well as polyethylene glycol (PEG)." (PMID 33303817, 2020). "In a recent study infection-related and all-cause death predicted by the GNRI and by serum Cr were comparable, indicating that serum albumin-based surrogates and serum Cr-based surrogates are equally useful for the prediction of mortality in hemodialysis patients." (PMID 32238848, 2020). "Therefore, under conditions of variable albumin/globulin ratios (especially during infection), SIG and Atot should be calculated on basis of albumin as well as on basis of total protein and should be interpreted together." (PMID 33315933, 2020). "Similarly, there was a significant decrease in the contents of albumin, total protein, and triglyceride and a significant increase in the contents of alanine aminotransferase and aspartate amino transferase after infection." (PMID 32846893, 2020). "Notably, fish with high infection densities had decreased plasma albumin and increased globulin levels, resulting in reduced albumin to globulin ratio." (PMID 32995005, 2020). "The very low relative albumin concentrations in dogs infected with B. gibsoni suggest severe inflammatory processes with possible serious alterations in the affected dogs (despite no serious abnormalities and clinical signs suggestive of the infection)." (PMID 33144631, 2020). "ALB and AST levels increased in mono-infection group, but ALB levels were decreased." (PMID 32295161, 2020). "In cases of disease, including infection, the half-life of albumin can be reduced." (PMID 32992538, 2020). "Clinical biochemistry markers were evaluated to monitor organ function throughout infection which indicted mild increases in albumin (ALB), total protein (TP), alkaline phosphatase (ALP) and calcium (CA) in all groups and elevated blood urea nitrogen (BUN) levels in the intranasal group." (PMID 32411730, 2020). "While unadjusted analysis demonstrated significant association between PGA levels, in-hospital mortality and composite outcomes, multivariate analysis revealed that cardiovascular state (i.e. heart rate and plasma albumin) are more important predictors for infection-induced complications." (PMID 32576856, 2020). "Neither did adjustment for serum albumin as a possible marker for poor nutritional status have any impact on the risk of an incident infection." (PMID 32405672, 2020). "The much higher affinity of human serum albumin for hemin with a binding constant of 10 nM−1 51 indicates that, during infection of humans, Mtb predominantly uses the albumin pathway for heme uptake when blood is available, e.g., in destroyed lung tissue with extracellular Mtb55." (PMID 31534126, 2019).
infection (continued). "Based on our findings, hemoglobin and albumin levels could be used for UTI risk assessment, and improving nutritional status should be taken as an infection prevention strategy." (PMID 30781460, 2019). "Patients with AD/ACLF have prostaglandin E2–mediated immune suppression, which can be reversed by administration of albumin; infusion of 20% human albumin solution (HAS) might improve outcomes of infections." (PMID 28911947, 2018). "To test this hypothesis, we treated WT mice with IFN-β or control (bovine serum albumin [BSA]) 24 h prior to infection with C. albicans and measured survival." (PMID 29666281, 2018). "As we know, albumin levels tend to decrease in patients with infection." (PMID 29995751, 2018). "We observed the decline of human ALB concentration in peripheral blood at 5 weeks post-infection." (PMID 29361613, 2018). "Recently, the CRP/albumin ratio, a combination of markers for systemic inflammation and nutritional status, has been extensively studied as an independent prognostic marker in patients with infection, malignancy, and other diseases." (PMID 30297655, 2018). "This interesting result could be partly explained by the differential predictive value of serum albumin for cardiovascular and infection-related mortality according to dialysis modality." (PMID 29494637, 2018). "Since most causes of death were due to excess bleeding and to a lesser extent to infection of the albumin or improper closing of the amnion around the chickens, rather than a defect in the chickens themselves, we do not expect a survivorship bias in our assessments." (PMID 30218045, 2018). "In SSI group, the infection rate was 2.96 % (143/4837) in the albumin <3.5 g/dL group and 1.00 % (1070/106,641) in the albumin >3.5 g/dL group, (RR = 2.39, 95 % CI [1.57 3.64], which was statistically significant (Z = 4.06, p < 0.0001) in a random model (I2 = 68 %)." (PMID 28093079, 2017). "Lastly, EAAs can reduce infection, which negatively impacts albumin and HB syntheses." (PMID 28635634, 2017). "In this study, observed differences in hematological and serum biochemistry values post-infection were limited to increases in albumin (all 3 rhinoceroses) and ALP (PB1 and PB4), mildly decreased total white blood cell count, and decreased eosinophil counts in PB1 and PB2." (PMID 28686714, 2017). "We thus investigated effects of DENV (serotype 2) infection on transcellular transport of albumin, the main oncotic plasma protein, through human endothelial cell monolayer by Western blotting, immunofluorescence staining, fluorescence imaging, and fluorometry." (PMID 27546060, 2016). "The higher infection related mortality in group A and B patients and its correlation with lower serum albumin might be related more HD catheter infections." (PMID 27752119, 2016). "Thus, it is likely that the presence of these CD4 T cells is helping to dampen inflammatory mediators in the young lungs during infection, especially since these mice have very low levels of albumin in their lungs indicating minimal lung damage." (PMID 27177221, 2016). "At day 5 post-infection, intra-nasal administration of rfhSP-D prior to N. brasiliensis infection significantly reduced intestinal burdens of adult N. brasiliensis in rfhSP-D-treated mice compared to bovine serum albumin (BSA)-treated controls." (PMID 26900854, 2016). "Paenibacillus was also observed in the secondary reproductive organs, namely muciparous and albumin glands, which could be a sign of vertically transmitted infection from parent to offspring." (PMID 25719489, 2015). "Furthermore, we excluded more than one third of the samples that were visibly contaminated by blood, or had high albumin/creatinine ratio or nitrite content to avoid patients with possible infection or kidney dysfunction." (PMID 26460890, 2015).
infection (continued). "We next wanted to mimic a native infection scenario using animal sera (sheep and goat) to demonstrate the enrichment capabilities of the Nanotrap particles in these complex solutions containing various host proteins (such as albumin)." (PMID 26020252, 2015). "We speculated that patients with higher APACHE II score might have more severe infection, more aggravated capillary leak, and then suffer more rapid albumin reduction (Gatta, Verardo & Bolognesi, 2012; Nicholson, Wolmarans & Park, 2000)." (PMID 26557421, 2015). "On the other hand, in cases with preserved albumin levels and low NGAL levels, serum albumin levels may decrease once severe infection develops and reduced albumin levels may persist even after recovery from infection." (PMID 26161663, 2015). "This included elevation of alanine aminotransferase (1 patient), elevation of alkaline phosphatase and reduction of albumin (1 patient), liver decompensation (defined as ascites unrelated to disease progression; 5 patients), and i.v. port infection (1 patient)." (PMID 26169362, 2015). "In contrast, albumin concentrations in SOCS1−/−IFN-γ−/− airways were significantly decreased at 11 dpi, indicating that SOCS1 deficiency is associated with attenuated lung vascular damage at the resolution phase of infection." (PMID 25500584, 2014). "The infection was likely to be severe and prolonged, as suggested by low serum albumin levels and a rise in C-reactive protein to a maximum of 18.03mg/dl on day 24, though symptoms of infection in this patient may have been masked by glucocorticoid use." (PMID 24524438, 2014). "In the animal model indomethacin and infection caused a poor clinical state, a great number of reisolated bacteria, elevated white blood cell (WBC) count, decreased C-reactive protein (CRP) and serum albumin levels." (PMID 25001579, 2014). "However, the infection induced a reduction of albumin levels in those fed with the standard protein diet (14%INF)." (PMID 24586759, 2014). "Albumin was the main protein detected in infected hamster urine during the end stage of infection." (PMID 24884439, 2014). "Serum albumin levels are lowered by infection and inflammation, and they decrease as a consequence of acute phase inflammatory reactions, in which increased cytokines switch protein synthesis in the liver from albumin to other phase proteins, and serum albumin falls." (PMID 23947772, 2013). "These associations remained unaltered even after adjusting for age, sex, Sequential Organ Failure Assessment (SOFA) score, Charlson Comorbidity Index, renal replacement therapy, albumin, hemoglobin, lactate, C-reactive protein and infection sites in multivariable models." (PMID 24321201, 2013). "The combination of prior CVA, preoperative sodium and albumin, postoperative sodium, hematocrit and albumin, and postoperative infection could discriminate patients who develop NCs with a discriminant probability of 76.6%." (PMID 22970403, 2012). "Based on our finding that bound HPV particles become decorated with HS and are released from cells plus the fact that main constituents of serum include albumin and GF, we performed the reciprocal experiment and tested whether GFs facilitate infection." (PMID 22346752, 2012). "In addition, albumin is a plasma protein and part of the inflammatory cascade induced by various stimuli such as mechanical ventilation or infection." (PMID 23091635, 2012). "Serum and CSF albumin and immunoglobulin concentrations by stage of infection." (PMID 23145191, 2012). "In contrast, serum ALB decreased gradually through the course of the infection, which may reflect alterations in vascular permeability or nutritional status." (PMID 22022624, 2011). "Such masking of the viral gp120/gp41 envelope complex might be a simple but promising strategy to inactivate HIV-1 and therefore prevent infection when HOCl-modified serum albumin is applied, for example, as a topical microbicide." (PMID 20525179, 2010).
infection (continued). "Notably, with the YFV model, serum albumin drops significantly on days 5 and 6 of infection, which is more proximal to the time at which we observed evidence of vascular leak (day 6 in the liver and day 7 in the small intestine) by the EBD method." (PMID 20846417, 2010). "Clinically relevant factors that were significantly associated with cycle 1 FN were older age, increasing planned cyclophosphamide dose, increasing planned etoposide dose, a history of previous chemotherapy, a history of recent infection, and low baseline albumin <35 g/l." (PMID 19055662, 2009). "However, both NNIS and preoperative albumin had low sensitivity for predicting postoperative infections." (PMID 17505683, 2007). "A significant (p < 0.05) decrease in serum total protein and albumin count on different days post-infection in the infected chicks compared to their controls could be attributed to severe liver damage, resulting in malfunctioning of the liver and decreased protein synthesis." (PMID 41568335, 2025). "Recent research suggests thatthe CRP/albumin ratio may be a novel marker of infection severity." (PMID 40622101, 2025). "Albumin, with its antioxidant and anti-inflammatory properties, is neuroprotective, while CRP is a commonly used inflammatory marker in clinical practice to reflect the degree of inflammation at the onset of infection and is associated with the severity, infarct size, and prognosis of AIS patients." (PMID 40697568, 2025). "Several potential confounders that may influence TTV levels and the infection risk were not accounted for in our study, including nutritional status, serum albumin levels, and co-infections with other viruses." (PMID 40981327, 2025). "Notably, the albumin-to-globulin ratio (AGR) was significantly lower in the infection group (median 1.1, IQR 0.93–1.35) compared with the aseptic group (median 1.5, IQR 1.32–1.7; p < 0.001), supporting its potential role as an adjunctive biomarker in the diagnostic assessment of PJI." (PMID 40603631, 2025). "For every 0.1 mg/dL increase in albumin levels, the risk of death from BSI after LT decreases by 0.81 times, indicating that maintaining higher albumin levels may help reduce the risk of postoperative infections." (PMID 40281777, 2025). "Moreover, serum albumin levels may also be influenced by nutritional status or metabolic conditions, which could confound their role as infection-specific markers." (PMID 40943972, 2025). "One of possible mechanisms of using albumin in preventing patients from nosocomial colonization and infection was it could enhance the antimicrobial activity of vasostatin-I, a kind of antibacterial chromogranin-derived peptide in vivo, with its antioxidative ability." (PMID 38659068, 2024). "So evaluating albumin independently of infection could lead to incorrect results." (PMID 38611651, 2024). "However, 25% albumin produced from human serum has been limited in use due to the risk of infection, and for this reason its use has not become widespread." (PMID 37423960, 2024). "However, the infection rate proposed here might be overestimated due to the downregulation of human ALB transcripts in primary human hepatocytes cocultured with mouse fibroblasts." (PMID 39639330, 2024). "Notably, age (OR 1.02; 95% CI 1.01–1.04; p = 0.010), vascular disease (OR 9.28; 95% CI 2.04–42.20; p = 0.004), infection originated from abdomen (OR 2.31; 95% CI 1.02–5.22; p = 0.044), and level of albumin (OR 0.89; 95% CI 0.84–0.94; p = 0.000) were shown to be associated with hypovitaminosis C." (PMID 38429378, 2024). "Albumin, a multifunctional protein with roles in antioxidant defense, anti-inflammatory action, and maintenance of vascular endothelial function, has been shown to mitigate the detrimental effects of infection-driven inflammatory responses on the body and reduce the incidence of organ failure." (PMID 37790597, 2023).
infection (continued). "In this study, significant differences in several clinical indicators (infection, ascites, urea, Na+, ALB, WBC, PLT, etc.)were observed between the progressive and stable groups, which may to some extent reflect changes in systemic inflammation and portal pressure, as suggested in previous studies." (PMID 36977956, 2023). "Furthermore, albumin has previously been shown to be an effective indicator in identifying patients at risk of a negative outcome, especially those with an infection and an apparently stable clinical state." (PMID 38137746, 2023). "This indicates that the presence of albumin in the urine in this group is not solely due to infection-related inflammation but may be indicative of an underlying condition of albuminuria." (PMID 37958262, 2023). "Moreover, serum albumin detection is inexpensive and practical, making it an ideal biomarker for clinical decision-making, such as aggressive nutritional intervention and effective infection control before UCBT." (PMID 37155023, 2023). "Therefore, the possible cause of the prolonged hospitalization in patients receiving albumin might have been related to postoperative infection, which may result in longer hospitalization after major abdominal surgery." (PMID 36768655, 2023). "In addition, the albumin to globulin ratio can serve as an infection predictive factor, as it may indirectly reflect immune competence." (PMID 35162137, 2022). "Therefore, preoperative optimization of nutritional status, perioperative monitoring of albumin, and careful intraoperative operation to avoid dural injury may help prevent surgical site infection." (PMID 36050996, 2022). "Thus, circumstantial factors, such as a zinc-enriched meal, time of day, albumin levels and infection, might affect the acute zinc status." (PMID 35807763, 2022). "However, studies have demonstrated that the use of albumin after surgery will not reduce the risk of postoperative incision complications and will increase the risk of postoperative infection." (PMID 35187165, 2022). "Therefore, the higher CRP level and PCT level and lower ALB level in the PJP+CMV group may also be representative of more severe infection and serious inflammatory response." (PMID 35479953, 2022). "Interestingly, patients with PLA requiring hospitalization for more than 28 HDs were specifically characterized by older age, male sex, a low albumin level and infection with unidentified pathogens compared to those requiring hospitalization for longer than 14 HDs." (PMID 36292245, 2022). "Besides, a low serum albumin level might decrease the resistance to infection, thus prolonging the healing time of wounds and increasing the postoperative drainage volume." (PMID 33510284, 2021). "Urine albumin and urine creatinine were collected a single time at the first study visit; transient microalbuminuria can occur due to fever, recent exercise, elevation in blood pressure, infection, such that the amount of falsely increased urine albumin levels cannot be determined." (PMID 34570768, 2021). "In addition, serum albumin levels have been proposed as a biomarker that represents the prior status of the individual, as a prognostic factor and also as a result of the acute response to infection." (PMID 34768653, 2021). "The inclusion of infection status as a significant predictor of the variability in Vc and Vp1 may reflect some element of confounding insomuch as infected patients had lower serum albumin concentrations relative to healthy volunteers." (PMID 34398673, 2021). "In addition, many factors have been identified to have possible effects on serum zinc concentration unrelated to dietary intake of zinc, for example infection and inflammation, time of day, inhibitors of zinc absorption such as phosphorus in the form of phytate and levels of albumin." (PMID 34224055, 2021).